LY9 (lymphocyte antigen 9)
Description:
Self-ligand receptor of the signaling lymphocytic activation molecule (SLAM) family. SLAM receptors triggered by homo- or heterotypic cell-cell interactions are modulating the activation and differentiation of a wide variety of immune cells and thus are involved in the regulation and interconnection of both innate and adaptive immune response. Activities are controlled by presence or absence of small cytoplasmic adapter proteins, SH2D1A/SAP and/or SH2D1B/EAT-2. May participate in adhesion reactions between T lymphocytes and accessory cells by homophilic interaction. Promotes T-cell differentiation into a helper T-cell Th17 phenotype leading to increased IL-17 secretion; the costimulatory activity requires SH2D1A. Promotes recruitment of RORC to the IL-17 promoter. May be involved in the maintenance of peripheral cell tolerance by serving as a negative regulator of the immune response. May disable autoantibody responses and inhibit IFN-gamma secretion by CD4(+) T-cells. May negatively regulate the size of thymic innate CD8(+) T-cells and the development of invariant natural killer T (iNKT) cells (By similarity).
Synonyms: SLAMF3; CD229; mLY9; hly9
Tractability: Antibody: UniProt places it where antibodies can reach, with high confidence; its Gene Ontology location is reachable by antibodies, with high confidence; UniProt predicts a signal peptide or a membrane-spanning region; the Human Protein Atlas places it where antibodies can reach. PROTAC: ubiquitination databases record sites on it.
Gene: Protein-coding gene on chromosome 1 (160,796,074 to 160,828,483, forward strand). Ensembl gene ENSG00000122224.
Subcellular location: Membrane; Cell membrane
Subcellular location (Human Protein Atlas): Plasma membrane; Centriolar satellite; Predicted to be secreted
Gene Ontology:
Biological process: positive regulation of interleukin-17 production; T-helper 17 cell lineage commitment; immune response; T cell activation
Cellular component: plasma membrane; external side of plasma membrane; cell surface; membrane
Genetic constraint (gnomAD): Loss-of-function variants: 55 observed, 62.68 expected, observed/expected ratio (o/e) 0.88, 90% interval 0.71 to 1.1. The upper end of that interval is the gene's LOEUF score, 1.1, which puts it in group 4 of 6, group 1 being the genes least tolerant of losing a copy. Missense variants: 777 observed, 827.36 expected, observed/expected ratio (o/e) 0.94, 90% interval 0.88 to 1. Synonymous variants: 281 observed, 323.16 expected, observed/expected ratio (o/e) 0.87, 90% interval 0.79 to 0.96.
Homologues: Orthologues: chimpanzee LY9 (97% identical), pig LY9 (60% identical), dog LY9 (57% identical), mouse Ly9 (55% identical), rat Ly9 (53% identical), zebrafish si:cabz01074946.1 (7% identical). Paralogues in human: CD84 (14% identical), SLAMF6 (14% identical), SLAMF7 (13% identical), SLAMF9 (12% identical), SLAMF1 (11% identical), CD2 (11% identical), CD244 (9% identical), SLAMF8 (8% identical), CD48 (6% identical).
Diseases named in the same sentence as LY9 in open-access papers:
LY9 is named in the same sentence as 54 diseases in open-access papers, as found by Europe PMC text mining. Sharing a sentence is not in itself a finding about the gene and the disease. The quoted sentences say what the papers report.
myeloma (14 papers, 2018 to 2025). "Validating our strategy, we identified nearly all known canonical diagnostic markers and immunotherapeutic targets in myeloma, including BCMA, CD138/SDC1, CD38, CD56, SLAMF7/CS-1, CD46, Integrin-b7 (ITGB7), CD74/HLA-DR, TACI, CD48/ SLAMF2, and LY9/CD229." (PMID 36311892, 2022). "The functional role of Ly9 on NK cells is unknown; however, a Ly9-engineered CAR T cell therapy has shown beneficial anti-tumour effect in murine models by targeting CD229hi myeloma cells which suggests Ly9 acts as an activating receptor." (PMID 35865550, 2022). "Recently, the SLAM receptor CD229/LY9 has been used as potential target for chimeric antigen receptor (CAR) T cell therapy in MM due to its strong and broader expression on the surface of BM plasma cells from MM and MGUS patients and on chemotherapy-resistant myeloma precursor cells." (PMID 33194767, 2020). "Notably, across these lines we detected almost all of the major immunotherapy targets in myeloma, as well as canonical flow cytometry markers for plasma cells: BCMA, CD138/SDC1, CD38, CD56, SLAMF7/CS-1, CD46, Integrin-b7 (ITGB7), CD74/HLA-DR, TACI, CD48/SLAMF2, and LY9/CD229." (PMID 35840578, 2022).
lupus (6 papers, 2008 to 2022). "Subtle changes were also observed in the relative proportions of naïve and/or memory B-cell and T-cell populations, and in a recent study these T cells changes were associated with a single nucleotide polymorphism in Ly9, which was linked to lupus." (PMID 18783591, 2008). "We recently showed that a nonsynonymous single nucleotide polymorphism in the SLAM molecule Ly9 is linked to development of lupus in our collection of trios." (PMID 18783591, 2008). "Diseases associated with LY9 include Systemic Lupus Erythematosus." (PMID 29371858, 2018). "Thus, an Ly9 mutation confers a predisposition to autoantibody generation, but one that may require additional factors (e.g., a viral infection or additional gene alterations) before a full lupus disease pathogenesis becomes evident." (PMID 23914190, 2013). "By contrast, other SLAMF receptor-deficiencies embedded in the BALB/c genome, such as Slamf1−/−(BALB/c.129) and Slamf2−/−(BALB/c.129), do not develop any autoimmune response, underscoring the role played by Ly9 as a negative regulator in the pathogenesis of lupus." (PMID 23914190, 2013). "Nonetheless, the functional role of Ly9 in lupus pathogenesis remains unknown." (PMID 23914190, 2013). "Our data also revealed a slightly increased frequency in the occurrence of the most immature B-cell lineages, multipotent progenitor (MMP) and Pro-B cells in the bone marrow of Ly9-deficient mice (data not shown), which is a variation that has been observed in other lupus-prone mice." (PMID 23914190, 2013).
lymphoma (5 papers, 2019 to 2025). A malignant (clonal) proliferation of B- lymphocytes or T- lymphocytes which involves the lymph nodes, bone marrow and/or extranodal sites. "We then made LY9-knockout (KO) HuT78 T-lymphoma cells transduced with cDNAs corresponding to WT LY9 or the patients’ variants." (PMID 40446017, 2025). "Indeed, complementation with WT LY9 via lentiviral transduction, unlike empty vector (EV), was sufficient to promote IFN-γ secretion induced by THP-1 plus HKMTb plus CytoStim in LY9-deficient CD4+ T-blasts or LY9 KO HuT78 T-lymphoma cells." (PMID 40446017, 2025). "Isogenic experiments showed that LY9 KO in CD4+ αβ T lymphocytes and HuT78 T-lymphoma cells impaired the upregulation of T-bet and RORγT induced by polyclonal stimuli or coculture with Raji B lymphoma cells (with or without LY9 KO) plus blinatumomab." (PMID 40446017, 2025). "Lymphoma patients (Ly1 and Ly2) and cancer-free TET2delA carriers (Ly9, Ly11, and Ly14) were also compared and no skewing toward hypermethylation was observed, although the results should be interpreted with caution due to low number of individuals in this comparison." (PMID 30890702, 2019).
autoimmune disease (4 papers, 2013 to 2022). A disorder resulting from loss of function or tissue destruction of an organ or multiple organs, arising from humoral or cellular immune responses of the individual to their own tissue constituents. "The results of this study demonstrate that antibody targeting of the cell surface molecule Ly9 (CD229) can restrain spontaneous autoimmune disease in a mouse model of SjS." (PMID 30519241, 2018). "We next assessed the role of Ly9 in autoimmune disease without the confounding influence of mixed haplotypes by utilizing Ly9−/−(BALB/c.129) mice." (PMID 23914190, 2013).
Autoimmunity (3 papers, 2013 to 2022). The occurrence of an immune reaction against the organism's own cells or tissues. "In examining the T-cell signature of Ly9 deficiency-mediated autoimmunity, the most remarkable difference we observed was in Tfh cells, which showed a threefold percentage increase and cell number expansion." (PMID 23914190, 2013). "In order to begin to understand why Ly9-deficient mice developed spontaneous autoimmunity, we search for any abnormal peripheral B and T cell development prior to full autoantibody disorder on 8- to 12-week-old Ly9-deficient mice." (PMID 23914190, 2013). "Further investigation will be required to elucidate the precise mechanism by which Ly9 confers protection from autoimmunity." (PMID 23914190, 2013). "In addition, PMA/ionomycin activation of splenic cells revealed that Ly9-deficient mice foster CD4+ T, CD8+ T, and iNKT cells capable of secreting major quantities of IFN-γ prior to the development of autoimmunity." (PMID 23914190, 2013). "Nonetheless, this study demonstrates that Ly9 may not only prove to be a valuable target for the treatment of autoimmunity, but may also help build a more rational road map toward understanding the molecular causes of SLE syndrome." (PMID 23914190, 2013). "We conclude that Ly9 gene ablation in a BALB/c background results in the disturbance of B and T cell subsets involved in autoimmunity, with major differences occurring in both Tfh cells and GC B cells." (PMID 23914190, 2013).
B-cell lymphoma (2 papers, 2022 to 2025). "Top proteins that were consistently associated with B-cell lymphoma across the EPIC, ARIC and UK Biobank cohorts included: CXCL13, sCD23, FCRL1, FCRL3, SEMA7A, CD72, CD48, LY9 and VCAM1." (PMID 40894013, 2025).
breast carcinoma (2 papers, 2018 to 2020). "A previous study showed LY9 was related to the cancer progression and correlated to overall survival of the patients with breast cancer." (PMID 32855654, 2020). "A total of three has-miR-542-5p target mRNAs were closely related to overall survival of breast cancer patients in both KMPD and GEPIA, and these are: YWHAB, LY9, and SFRP1." (PMID 29371858, 2018). "Regulating the target genes YWHAB, LY9 and SFRP1 may be a possible mechanism of has-miR-542-5p in TamR of breast cancer." (PMID 29371858, 2018).
ovarian carcinoma (2 papers, 2021 to 2024). A malignant neoplasm originating from the surface ovarian epithelium. "Moreover, LY9 and SLAMF1 were identified as the real hub genes associated with the overall survival of ovarian cancer patients by affecting the infiltration of activated B cells." (PMID 34461858, 2021). "Finally, LY9 and SLAMF1 were recognized as the real hub genes in immune infiltrates of ovarian cancer." (PMID 34461858, 2021). "LY9 and SLAMF1 might be potential therapeutic targets of ovarian cancer." (PMID 34461858, 2021). "Thus, the expression of LY9 and SLAMF1 was higher in ovarian cancer tissues than in normal ovarian tissues, and the high expression of these 2 genes was relevant to the prognosis of ovarian cancer." (PMID 34461858, 2021).
Sjögren's Syndrome (2 papers, 2018 to 2021). "For example, it has been reported that LY9 antibody targeting depletes marginal zone and germinal center B cells in lymphoid tissues and reduces salivary gland inflammation in a mouse model of Sjögren's Syndrome." (PMID 33722258, 2021).
Splenomegaly (2 papers, 2013 to 2018). Abnormal increased size of the spleen. "Moreover, aged Ly9-deficient mice spontaneously develop features of systemic autoimmunity, such as splenomegaly and the production of anti-nuclear, anti-dsDNA, and anti-nucleosome autoantibodies, indicating that the Ly9 cell surface receptor is involved in the maintenance of immune cell tolerance." (PMID 30519241, 2018).
asthma (1 paper, 2025). "The large SVs also contained genes related to immune response, such as LY9, ITLN2, and CHIA, which may be linked to asthma susceptibility in the JH pig." (PMID 40372724, 2025).
Chlamydia infection (1 paper, 2019). "Moreover, treatment with anti-Ly9 antibody that deplete the MZB cell population rendered NOD mice more efficient in inducing enhanced Th1 immune responses and clearing the infection, thus supporting a regulatory role for this cell subset in our model of Chlamydia infection of the male genital tract." (PMID 30881362, 2019).
diabetic nephropathy (1 paper, 2025). "LY9 (SLAMF3) is an immune coreceptor regulating T/NK-cell activation and cytokine release, thereby shaping the inflammatory milieu that can interface with adiposity and downstream microvascular injury (consistent with its methylation signal in diabetic nephropathy)." (PMID 41340073, 2025).
glomerulonephritis (1 paper, 2013). A renal disorder characterized by damage in the glomeruli. "Although we observed a mild increase in IgG-immunocomplex deposits in Ly9-deficient mice, this initial trait prior to any sign of glomerulonephritis did not trigger a renal pathology." (PMID 23914190, 2013).
hemophagocytic lymphohistiocytosis (1 paper, 2022). "The other two genes (LY9 and STXBP2) cause or are linked to hemophagocytic lymphohistiocytosis (HLH) disorders, including macrophage activation syndrome (MAS)." (PMID 36588876, 2022).
Obesity (1 paper, 2018). Accumulation of substantial excess body fat. "In our previous study, we reported that 14 adipocyte genes (Ccl7, Emr1, Evi2a, Gusb, H2-DMb2, Lcp1, LOC100041137, Ly9, Ptpre, Rgs1, sc1000528.1_16, Sirpa, Sfrp5, and Acacb) were associated with both advanced age and diet-induced obesity." (PMID 30282902, 2018).
tuberculosis (1 paper, 2025). A chronic, recurrent infection caused by the bacterium Mycobacterium tuberculosis. "Impaired CD4+ T cell-dependent IFN-γ immunity in LY9-deficient humans underlies tuberculosis." (PMID 40446017, 2025).
tumor (22 papers, 2013 to 2025). "Here we show that the expression of the Signaling Lymphocyte Activation Molecule (SLAM) family members CD48 and Ly9 (CD229) by MHC-I-deficient tumor cells significantly contributes to NK cell activation." (PMID 27054584, 2016). "We conclude that CD48 and Ly9 significantly contribute to NK cell activation in response to a classical “missing-self” tumor target cell." (PMID 27054584, 2016). "Based on TCGA and GTEx data, the mRNA expression levels of LY9 and SLAMF1 were significantly higher in tumor tissues than in normal ovarian tissues." (PMID 34461858, 2021). "When all tumor samples were evaluated together the correlation of GZMH, ABL1, IL-7, LY9, IL-12, SCAMP3, and CD244 were highly significant (p < 1 × 10−6)." (PMID 29587383, 2018). "In addition, LTB, IL1A, LY9, and SLAMF7 were differentially expressed between normal and tumour tissues." (PMID 33397394, 2021).
cancer (13 papers, 2016 to 2025). A tumor composed of atypical neoplastic, often pleomorphic cells that invade other tissues. "To explore this mechanism in human cells, we first primed monocyte-derived macrophages from cancer-free TET2delA carriers (Ly9, Ly11, and Ly14) and controls (Ly8 and an unrelated control) with lipopolysaccharide (LPS) and interferon-γ, followed by stimulation with NLRP3 inflammasome activators." (PMID 30890702, 2019). "Interestingly, many of the DMGs identified had multiple roles and several were potential cancer biomarkers or were previously shown to be implicated in various types of cancers, including ABLIM1, ADAM12, ARHGEF4, FBLN2, ITGA6, LRPAP1, Ly9, NT5E, PITPNC1, PLCG1, OBSCN, RHOH, SPTBN1, SPOCK2 and SPRY1." (PMID 41159936, 2025).
infection (8 papers, 2010 to 2021). The state of being infected such as from the introduction of a foreign agent such as serum, vaccine, antigenic substance or organism. "There were expression differences in Cd244, but not Itln1 or Ly9, over the course of infection between resistant C57BL/6 and susceptible A/J and BALB/c." (PMID 21085469, 2010). "Interestingly, discrimination analysis identified a number of T cell-related genes (e.g., IL7R, LY9, and TCP1) that were uniquely upregulated with Makona-C07 infection, which may reflect aberrant T cell activation associated with fatal outcomes in EVD patients." (PMID 34484156, 2021). "The expression of Ly-9 and CD3 RNA increased in all brain regions upon infection, with the highest level in the olfactory bulb of 93/783- and Torö93E-infected mice." (PMID 32988388, 2020). "At the site of infection, expression of the SLAM family members CD48, CD229 (LY9), CD319 (CRACC), and CD352 (NTBA) may be particularly important for the interaction of PDC with NK and T cells." (PMID 22312349, 2011).
LY9 also shares sentences with these, for which no sentence is quoted: hepatocellular carcinoma (6 papers); multiple myeloma (5); hematologic disorder (3); type 2 diabetes (3); Burkitt lymphoma (2); hematopoietic cancer (2); leukemia (2); MALT lymphoma (2); multiple sclerosis (2); viral infection (2); alveolar rhabdomyosarcoma (1); B-cell neoplasm (1); chronic lymphocyte leukemia (1); colorectal cancer (1); diabetes (1); diffuse large B-cell lymphoma (1); Friedreich ataxia (1); hepatitis C virus infection (1); lymphopenia (1); macrophage activation syndrome (1); marginal zone lymphoma (1); melanoma (1); metastasis (1); metastatic tumors (1); monoclonal gammopathy of undetermined significance (1); neuroblastoma (1); Neurologic disorder (1); Oral ulcer (1); plasma cell dyscrasias (1); plasma cell leukemia (1).
A further 4 diseases each share a sentence with LY9 in 1 paper.